MPO (myeloperoxidase)
Diseases named in the same sentence as MPO in open-access papers (continued):
Sharing a sentence is not in itself a finding about the gene and the disease.
tumor (continued). "In addition, we detected H3Cit and another indicator of NETs formation, the myeloperoxidase-DNA (MPO–DNA) complex, in the serum of tumor-bearing mice by ELISA51,52." (PMID 36934105, 2023). "While much more MPO+ CXCR2+ neutrophils are found in LN(+) tumor tissue than in LN(‐) tumor tissue." (PMID 36670069, 2023). "The MPO activity is lower in MDSCs from tumor-bearing mice compared to MDSCs from tumor-free mice." (PMID 38201509, 2023). "MPO is most well-known to be produced by neutrophils, but may also be produced by macrophages and may have the ability to induce apoptosis in tumor cells." (PMID 36376448, 2023). "MPO participates in the regulation of tumor growth, apoptosis, migration, and metastasis." (PMID 36768971, 2023). "Taken together, these findings indicate that MPO mRNA expression is highly upregulated within myeloid populations at early stages of MM tumour establishment, while an expansion of myeloid cells at late stage disease is accompanied by colocalisation of MPO activity." (PMID 37699574, 2023). "It is also believed that MPO influences tumor growth, apoptosis, and metastasis." (PMID 38062888, 2023). "MPO is reported to promote tumor initiation and progression." (PMID 36768971, 2023). "Interestingly, MM tumour cell homing was increased towards sites of elevated myeloid cell numbers and MPO activity within the BM." (PMID 37699574, 2023). "Interestingly, the levels of plasma MPO-DNA positively correlated with the number of citH3-positive cells in tumour tissues (r = 0.8613, p < 0.0001)." (PMID 37127629, 2023). "Furthermore, our pathology results showed that ETV4 expression levels positively correlated with infiltrated MPO+ or CD66b+ TANs levels in the tumor tissues." (PMID 36670069, 2023). "The immunohistochemical detection of MPO-positive neutrophilic granulocytes revealed a decreased number of inflammatory cells in the tumor tissue following ECT treatment compared to the rEP and BLM group (ECT 7.80 ± 2.6 cells per HPF; rEP 14.9 ± 1.4 per HPF; and BLM 18.6 ± 1.9 per HPF)." (PMID 36900388, 2023). "More MPO+ CXCR2+ neutrophils were identified in tumor tissue than in normal adjacent tissue." (PMID 36670069, 2023). "Finally, the dual roles played by neutrophils in cancer are so profound that even neutrophil proteins such as NE and MPO can directly exert and assist in pro- or anti-tumor functions where the duality mirrors neutrophils themselves." (PMID 36514901, 2022). "In this model, inhibition of MPO with N-acetyl lysyltyrosylcysteine amide also reduced tumor size." (PMID 36293108, 2022). "Other lipids found in MDSC from tumor-bearing mice were found to be in the oxidized form and could be attributed to ROS and myeloperoxidase (MPO)." (PMID 35408873, 2022). "The highest percentage of MPO positive cells was observed in the tumor + placebo group." (PMID 35887022, 2022). "Furthermore, it has been shown that CAFs mediate the activation of TGF-β/Smad3 signaling in tumor cells to induce IL-8 secretion and promote MPO+ neutrophil migration in lung cancer." (PMID 35158807, 2022). "Thus, the impact of MPO on tumor progression is likely multi-faceted, involving numerous signal transduction pathways and more work is warranted to gain a better understanding of the specific role of MPO in cancer." (PMID 36293108, 2022). "The tumor itself may also be to blame for the increase in MPO levels following anticancer therapy in addition to cardiotoxicity." (PMID 36551214, 2022). "As with MPO function, NETs have been suggested to both promote and inhibit tumor progression." (PMID 36293108, 2022). "The different cytotoxic compounds may subsequently contribute to the eradication of tumor cells, as different components isolated from neutrophil granules, including MPO, defensins, granzyme B and NE, were able to kill tumor cells." (PMID 35884427, 2022). "Either inhibiting or removing MPO restrains neutrophil-elicited tumor cell cytotoxicity." (PMID 36514901, 2022).
tumor (continued). "Moreover, as the cancer progressed, we found that the expression of MPO significantly increased in the tested tumor samples." (PMID 33763491, 2021). "Besides prognostic issues, the secretion of MPO by TANs is also important for the recruitment of monocytes and macrophages and the activation of platelets in tumor settings." (PMID 35003081, 2021). "Five days following tumor inoculation via the portal vein, we performed liver I/R which promotes neutrophil infiltration to the liver and formation of NETs (measured by quantitating serum MPO, tissue cit-H3 and flow cytometry)." (PMID 34899751, 2021). "At high concentrations, release of MPO and NE as important components of NETs have cytotoxicity effect on tumor cells, but reducing the release may result in the conversion of anti-tumor to pro-tumor function." (PMID 34660642, 2021). "In agreement with our hypothesis that tumour-derived IL-1B drives an anti-tumour response, we quantified the infiltration of neutrophils in primary tumours and found a tendency for an increase in MPO+ neutrophils." (PMID 34290237, 2021). "NETs play a pro-tumor role during tumor progression and metastasis by enhancing angiogenesis, extracellular matrix remodeling, and tumor cell proliferation through proteases such as MPO or NE or by trapping the circulating cancer cells and promoting metastasis and disease recurrence." (PMID 34458135, 2021). "MPO has been found in mature macrophages in atherosclerosis, in brain tissue showing Alzheimer-type pathology or Parkinson’s disease, and in multiple sclerosis lesions, but it is also released in the tumor immune microenvironment." (PMID 34944979, 2021). "However, quantifying the Dendra2 fluorescence, indicative of tumor growth over time, also demonstrated an increase in tumor growth in MPO−/− animals (reformatted and reanalyzed from our previously reported publication)." (PMID 33668735, 2021). "Checking myeloperoxidase activity, BcAEF reduced neutrophils migration towards the tumor." (PMID 32899132, 2020). "We then tested if MPO enzymatic activity is necessary for neutrophil-induced tumor cell death." (PMID 33110073, 2020). "Moreover, indium-111-neutrophil activity in the tumour biopsies also correlated with myeloperoxidase (MPO)-positive neutrophils." (PMID 32887739, 2020). "Inhibition or depletion of myeloperoxidase suppresses neutrophil-induced tumor cell cytotoxicity." (PMID 33110073, 2020). "To understand whether such neutrophil-derived MPO transfer into tumor cells required direct cell–cell contact, we employed two approaches." (PMID 33110073, 2020). "Tumor infiltrating immune cells, especially neutrophils and eosinophils, contribute to the generation and maintenance of the tumor inflammatory milieu by producing massively myeloperoxidase (MPO) and eosinophil peroxidase (EPO), respectively." (PMID 32604738, 2020). "As formerly described, Ehrlich carcinoma cells growth promoted a large migration and infiltration of neutrophils into the tumor microenvironment, since the Ehrlich-bearing mice in the vehicle group showed approximately 60 folds more MPO activity when compared to naïve mice in the satellite group." (PMID 32899132, 2020). "Innate immune system receptors such as TLRs 2, 5, 9, and the factors responsible for anti-microbial responses such as IL-12 subunit alpha (IL-12A), bactericidal/permeability-increasing protein (BPI), and myeloperoxidase (MPO) were expressed minor in the tumor in comparison with healthy tissue." (PMID 32117767, 2020). "Indeed, we observed a dramatic decrease in both total CD45+ globoid and MPO+ immune cells in the VI in CCR2KO tumor mice compared to WT tumor mice." (PMID 32391790, 2020). "However, hyperprogression was correlated with the density of myeloperoxidase myeloid cells within the tumor (p = 0.05) and inversely correlated with PD-L1 expression in tumor cells (p = 0.046)." (PMID 31151303, 2019).
tumor (continued). "Subsequent studies showed that it is closely related to myeloperoxidase from tumour cells." (PMID 31703576, 2019). "Most of the lipids detected in the MDSCs of tumor-bearing mice and cancer patients were found to be oxidized, possibly resulting from the oxidative activities of reactive oxygen species (ROS) and myeloperoxidase (MPO)." (PMID 31275326, 2019). "The application of this technology will not be limited to AML, where MPO-mediated ROS response can be used as a prognostic measure, but also in other cancers where tumor-associated neutrophils suppress T cell immunity via generation of ROS response." (PMID 29416750, 2018). "Tumor-infiltrated neutrophils in tumor tissues expressed higher levels of MPO and Fas/FasL, which may be involved in TAN-mediated inhibition of CD4+ and CD8+ T cells." (PMID 27446967, 2016). "Larger amounts of Ly6G+MPO+ neutrophils were found in 3LL tumor tissues." (PMID 27446967, 2016). "We found that CSC-derived EVs promoted persistent phenotypical changes in MSCs characterized by an increased expression of genes associated with cell migration (CXCR4, CXCR7), matrix remodeling (COL4A3), angiogenesis and tumor growth (IL-8, Osteopontin and Myeloperoxidase)." (PMID 25797265, 2015). "The results showed that G-CSF/IL-6 could not antagonize the priming effect of IFN-γ/TNF-α, evaluated by the activation of signaling pathways, MPO release, and tumor-suppressing effect of neutrophils." (PMID 25587026, 2014). "Therefore, the treatment with IFN-γ/TNF-α enabled T-sMs to induce anti-tumor function of the neutrophils by increasing the production and/or release of MPO, NE, and TRAIL, and reducing the expression of Bv8 and Mmp9 genes." (PMID 25587026, 2014). "Because inflammatory events have been implicated in carcinogenesis and neutrophil infiltration is correlated with some types of cancer metastasis, we used a multistage model of SCC to examine the involvement of ELA, MPO, NO, cytokines and inflammatory cells in tumour development." (PMID 23176085, 2012). "To further verify whether neutrophil infiltration and NET formation were enhanced by chemotherapy, we performed tissue immunofluorescence and ELISA detection of serum myeloperoxidase-DNA (MPO-DNA) complex in 4T1 tumor–bearing mice with Dox or vehicle treatments." (PMID 41480760, 2026). "Given that MPO is a key component of NETs, it is reasonable to hypothesize that MPO released from NETs could similarly modulate the redox environment and metabolic pathways within the tumor microenvironment, thereby influencing tumor growth and immune evasion." (PMID 39849606, 2025). "Collectively, these findings support a model in which MPO overexpression in advanced BLCA is linked to impaired N-glycan maturation and immune infiltration, with potential consequences for glycoprotein function and tumor progression, warranting in-depth investigations." (PMID 40430030, 2025). "Additionally, the study also demonstrated that exogenous lactate treatment can induce NETs formation.As a complex composed of various proteases (NE, MPO, HMGB1, etc.)and DNA, NETs and their associated components have been shown to significantly impact tumor metabolic reprogramming." (PMID 39849606, 2025). "Interestingly, circulating myeloperoxidase, elastase, and dsDNA are NETs biomarkers, indicating that liraglutide might reduce NETs in tumor‐bearing mice." (PMID 36271684, 2024). "Additionally, our previous work demonstrated that MPO inhibited tumor cell NF-κB signaling and we anticipate that MPO could similarly inhibit NF-κB signaling in T cells, decreasing T cell activation." (PMID 38367056, 2024). "Furthermore, the upregulation of MMP-2, MMP-3, and myeloperoxidase highlights the role of these tumors in host-immune interactions, while the decrease in osteopontin and proliferin suggests a shift toward a less favorable tumor microenvironment." (PMID 38890285, 2024).
tumor (continued). "Furthermore, neutrophils can undergo degranulation, a process during which molecules such as defensins, myeloperoxidase, and lysozyme are secreted from intracellular granules into the extracellular environment, leading to tissue damage and promoting tumor metastasis." (PMID 39654896, 2024). "Therefore, we investigated the effects of MPO inhibition on tumour growth in vivo." (PMID 37627581, 2023). "As MPO is commonly activated in inflammatory responses, we postulated that induction of inflammation, and recruitment of myeloid cells with increased MPO activity, may provide a supportive BM microenvironment to promote MM tumour development and growth." (PMID 37699574, 2023). "Unsurprisingly, other factors that may promote polyunsaturated fatty acid phospholipid (PUFA-PL) synthesis and peroxidation (such as FATP2 and MPO), or that may cause GPX4 inhibition (such as hypoxia in the tumor microenvironment), may also influence the inhibitory activity of tumor PMN-MDSCs." (PMID 36813764, 2023). "In addition, heterotopic tumors from CreERT2 mice showed diminished inflammation demonstrated by reduced presence of total leukocytes (CD45+ area), TAMs (CD68+ area), neutrophils (MPO+ cells), tumor-infiltrating lymphocytes, TILs (FOXP3+), as well as T regulatory cells, Tregs (FOXP3+CD4+ cells)." (PMID 35688943, 2022). "Interestingly, MPO+ neutrophils were also detected on histology in tumor regions where the gamma counts were low, implying the presence of tissue-resident neutrophils that were not accounted for when imaging radiolabeled neutrophils isolated from the peripheral blood." (PMID 34637051, 2022). "Besides differences in organs and models that have different immune environments, chronic low levels of MPO activity could serve to induce mutagenesis and promote tumorigenesis, especially during early tumor development." (PMID 34944979, 2021). "Interestingly, some peri-necrotic tumor cells appear to contain MPO puncta (magenta-outlined)." (PMID 33110073, 2020). "Moreover, a new biologic tripeptide inhibitor of MPO activity, N-acetyl lysyltyrosylcysteine amide (KYC), has been proposed as a treatment during the inflammatory stage in the early stages of tumor development, suggesting the use of MPO inhibitors in cancer prevention." (PMID 28448444, 2017). "Additionally, tumor-infiltrated neutrophils expressed higher levels of MPO and Fas/FasL, which may be involved in TAN-mediated inhibition of CD4+ and CD8+ T cells." (PMID 27446967, 2016). "This alternative role of MPO may represent a mechanism by which MSCs support tumor development." (PMID 25797265, 2015). "On the other hand, however, neutrophils could release TRAIL, myeloperoxidase (MPO) and neutrophil elastase (NE), which not only suppress angiogenesis and induce vascular disruption, but also induce apoptosis and inhibit the proliferation of tumor cells." (PMID 25587026, 2014). "This was evidenced in vivo by immunofluorescence, which showed upregulated levels of key NETs markers (MPO and CitH3) in PUS7‐overexpressing tumours." (PMID 41496500, 2026). "Tumor sections were also stained with antibodies for Ki67, cleaved poly‐ADP‐ribose polymerase (cPARP), CD31, and myeloperoxidase (MPO) to evaluate tumor cell proliferation, apoptosis, angiogenesis, and inflammation, respectively." (PMID 40644310, 2025). "Bone marrow biopsy revealed the presence of tumor cells, and immunohistochemical staining showed that the tumor cells were positive for CD34, MPO, and CD99, and weakly positive for PAX-5, suggesting a diagnosis of AML." (PMID 41561755, 2025). "Myeloperoxidase (MPO) produces hypochlorous acid (HOCl), a highly toxic molecule that damages tumor cell membranes, DNA, and proteins." (PMID 40227814, 2025). "Enhanced STAT3 activation in TANs leads to significantly reduced secretion of myeloperoxidase, neutrophil elastase, and TRAIL, while concurrently inducing markedly elevated expression of MMP9 and Bv8 genes, which favors tumor angiogenesis and growth." (PMID 41254689, 2025).
tumor (continued). "Notably, higher levels of Sphingomonas in healthy mammary tissue compared to tumor tissue have been linked to increased expression of Toll-like receptors (TLR2, TLR5, and TLR9) and antimicrobial effectors such as IL-12A, bactericidal/permeability-increasing protein (BPI), and myeloperoxidase (MPO)." (PMID 40599853, 2025). "In AOM/DSS-induced CRC mice, KGM-CUR/PSM microspheres significantly improved survival and inhibited CRC tumor growth, and effectively reduced the expression of inflammatory cytokines (TNF-α, IL-1β, IL-6) and myeloperoxidase (MPO)." (PMID 40733148, 2025). "Laboratory tests demonstrated elevated C-reactive protein (4.75 mg/dL), but some tumor markers (including CEA, CA19-9, and CA125), anti-nuclear antibodies, MPO-ANCA, PR3-ANCA, β-D-glucan, and interferon-gamma release assay were all negative." (PMID 40870884, 2025). "We observed significant decreases in Ki67‐positive tumor cell proportions, CD31‐positive blood vessel number and volume, and MPO‐positive neutrophil proportions in tumors admixed with exp‐CAF2‐shENG‐1 or ‐2 cells." (PMID 40644310, 2025). "Other key transcripts, such as MPO and DEFA3, further emphasize the role of neutrophil extracellular traps and their immune activity in tumor progression." (PMID 40003985, 2025). "IFN-α-primed N1 neutrophils exhibit heightened production of myeloperoxidase and hydrogen peroxide (H2O2), which induce DNA damage in tumor cells via oxidative stress pathways." (PMID 40387965, 2025). "N1 TANs restrict tumor growth by enhancing IL-18 expression in natural killer (NK) cells through INF-1 secretion and by directly inducing tumor cell death via myeloperoxidase, ROS, and related mediators." (PMID 41320679, 2025). "We found that while infiltration of CD15+MPO+ cells in PT correlated with NHG and Ki67, the presence of CD15−MPO+ cells correlated significantly with NHG, Ki67 and tumor size." (PMID 40652059, 2025). "In vivo efficacy was evaluated in AOM/DSS-induced CRC mice, monitoring tumor growth, inflammatory markers (TNF-α, IL-1β, IL-6, MPO), and gut microbiota composition." (PMID 40733148, 2025). "In contrast, the expression levels of MPO, ELA2, ARG1, and ICAM1 remained unchanged in all treatment groups, indicating that rhGDF15 and rhTNF-α have selective effects on tumor-promoting cytokine expression." (PMID 41035818, 2025). "Immunohistochemically, the tumor cells were positive for CD34, CD117, and myeloperoxidase (MPO) and focally positive for CD15." (PMID 39958139, 2025). "When dHL-60 neutrophils prelabelled with a lipophilic membrane fluorescent dye, PKH26, were cocultured with LN229TAZ(4SA) tumor cells, we observed that tumor cells contain PKH26+ puncta and MPO+ granules." (PMID 38806658, 2024). "3-IAA translocates to the tumour site by circulation and undergoes oxidation into toxic molecules (3-IAAP) by MPO and cytotoxic anticancer drugs (FOLFIRINOX) within intratumoral neutrophils." (PMID 38874485, 2024). "The tumor-immune composition of KPYC6419 subcutaneous tumors from WT and MPO−/− was evaluated using flow cytometry at tumor endpoint." (PMID 38367056, 2024). "Initially, we investigated the inhibition of myeloperoxidase (MPO) using its inhibitor, 4-ABAH, which significantly reduced necrosis in GBM and extended the survival of tumor-bearing mice." (PMID 38806658, 2024). "In this study, liraglutide substantially decreased circulating neutrophil extracellular trap (NET) markers myeloperoxidase, elastase, and dsDNA in Lewis lung cancer (LLC) and Hepa1‐6 tumor‐bearing mice." (PMID 36271684, 2024). "To delineate the possible mechanisms of MPO-mediated ICT enhancement, we isolated CD11b+Ly6G+ subsets from the spleen of tumor-bearing and healthy mice." (PMID 38367056, 2024). "Immunofluorescence results of HL‐60 cells cocultured with HL‐60 cells from METTL5‐sh and METTL5‐NC groups showed MPO/H3 expression in METTL5‐NC group was higher than METTL5‐sh group, consistent with tumor tissue results." (PMID 38613157, 2024).